ID1 (inhibitor of DNA binding 1)
Diseases named in the same sentence as ID1 in open-access papers (continued):
Sharing a sentence is not in itself a finding about the gene and the disease.
colon cancer (23 papers, 2010 to 2025). "Indeed, ID1 expression and TGFβ signal activity were positively correlated in Smad4-deficient colon cancer tissues with relatively high Nur77 expression." (PMID 33990575, 2021). "Thus, Smad4-deficient colon cancer cells not only evade TGFβ-induced growth inhibition through Smad4 deletion but also actively respond to TGFβ-induced tumor progression at least through ID1 stabilization, thus reflecting their high malignancy." (PMID 33990575, 2021). "In colon cancer stem cells, the combined expression of ID1 and ID3 promotes self-renewal and tumor initiation." (PMID 38195969, 2024). "In colon cancer, it has been demonstrated that ID1 and ID3 expression collaborate to regulate cancer stem cell self-renewal through cell cycle restriction mediated by the cell cycle inhibitor p21." (PMID 39676870, 2024). "Herein, we identified an enhancer, denoted E1, and determined its role in the regulation of ID1 expression in colon cancer." (PMID 37373188, 2023). "IHC analysis showed that ID1 protein expression levels were higher in 20 of 23 primary colon cancer tissues compared with adjacent normal tissues (86.96%)." (PMID 37373188, 2023). "Specifically, we found that the function of Nur77 in colon cancer is defined by its effects on ID1 expression and is switched by the strength of TGFβ signal." (PMID 33990575, 2021). "This is also consistent with previous findings that ID1 is a positive regulator in colon cancer cell stemness." (PMID 33990575, 2021). "Inhibitor of differentiation 1 (ID1) is a target gene of TGFβ and a key promoter for colon cancer progression." (PMID 33990575, 2021). "To further explore the pathophysiological relevance of the mechanisms discovered in vitro, we analyzed the correlation of Nur77 and ID1 expression in tissue samples from colon cancer patients." (PMID 33990575, 2021). "In conclusion, the mechanistic principles emerging from our study highlight the tightly integrated duality of Nur77 and TGFβ signaling in regulating ID1 expression as well as its implications in colon cancer development and treatment." (PMID 33990575, 2021). "ID1 expression contributes to the resistance of colon cancer to the chemotherapeutic drug oxaliplatin through upregulating cancer cell self-renewal capacity." (PMID 33990575, 2021). "Accordingly, we used in vitro three-dimensional (3D) cell sphere assay to analyze the effect of Nur77 and TGFβ on regulating ID1-dependent stemness of colon cancer cells." (PMID 33990575, 2021). "We also discovered that Nur77 has dual activity in regulating ID1 expression in colon cancer, a finding that likely reflects a combination of genomic and non-genomic mechanisms of Nur77." (PMID 33990575, 2021). "Our data therefore define the integrated duality of Nur77 and TGFβ signaling in regulating ID1 expression and provide mechanistic insights into the paradoxical roles of TGFβ and Nur77 in colon cancer progression." (PMID 33990575, 2021). "Future research will evaluate the potential of Nur77 ligands in downregulating ID1 expression, thereby providing clinical significance in colon cancer treatment." (PMID 33990575, 2021). "Here, we reveal an unanticipated crosstalk between Nur77 and TGFβ signaling in regulating ID1 expression at both transcriptional and post-translational levels, which is pathophysiologically relevant to colon cancer development." (PMID 33990575, 2021). "Together, these results indicate that Nur77 inversely correlates with ID1 expression and colon cancer metastasis in the environment of low TGFβ signaling in vivo." (PMID 33990575, 2021). "The previous study showed that Id1/Id3 regulates colon cancer-initiating cells (CC-ICs) by p21, and that, in colon cancer, Id1/Id3 protects the tumor-initiating ability of CC-ICs from oxaliplatin." (PMID 28143562, 2017). "In primary colon cancer samples Id1 and Id3 regulate the self-renewal of colon cancer stem cells (CSCs) via p21." (PMID 28122577, 2017).
colon cancer (continued). "Accordingly, Id1 levels are reduced in breast, prostate, lung and colon cancer cell lines treated with the small-molecule Src inhibitor AZD0530." (PMID 28122577, 2017). "Silencing of Id1 and Id3 together decreased self-renewal and increased sensitivity to chemotherapeutics of colon cancer-initiating cells." (PMID 24160469, 2013). "Expression of ID1 was readily detectable in all cervical cancer cell lines, in HaCaT, in the colon cancer line HCT-15 as well as in Jurkat (lymphocytic leukemia)." (PMID 20070914, 2010). "To test this hypothesis, we determined the role of the three putative ID1 enhancers in regulating ID1 expression and the TFs that regulate ID1 enhancer activity in colon cancer." (PMID 37373188, 2023). "High enhancer activity in a subset of human colon cancers can increase the expression of ID1 and promote cell proliferation, suggesting that enhancer E1 might be a potential target for anti-CRC drug studies." (PMID 37373188, 2023). "ID1 exerts its tumor-promoting effects by inhibiting the transcriptional function of several bHLH tumor suppressors, such as inhibiting the E2A-p21 axis to govern colon cancer-initiating cell self-renewal activity." (PMID 37996458, 2023). "Id1-knockout colon cancer EMT cells showed increased VE-cadherin and decreased Snail and Twist, indicating that regulating Id1 may have good prospects for reversing EndMT." (PMID 35049366, 2022). "miRNA-885-3p could also disrupt angiogenesis through regulation of BMPR1A and repression of BMP/Smad/Id1 signaling, thereby suppressing the growth of colon cancer cell xenografts." (PMID 36064409, 2022). "Here, the authors show a complex interplay between nuclear receptor Nur77 and Transforming Growth Factor-β (TGFβ) to regulate ID1 expression at both transcriptional and post-translational levels which is relevant to colon cancer stemness, metastasis and resistance to oxaliplatin." (PMID 33990575, 2021). "Thus, TGFβ converts Nur77’s role from destabilizing ID1 protein and cancer inhibition to inducing ID1 mRNA expression and cancer promotion, which is highly relevant to colon cancer stemness, metastasis and oxaliplatin resistance." (PMID 33990575, 2021). "Whether Nur77 regulates the TGFβ/ID1 axis and why Nur77 plays an opposite role in colon cancer development remain elusive." (PMID 33990575, 2021). "Thus, the effect of TGFβ on increasing colon cancer resistance to oxaliplatin appears to arise from its Nur77-dependent induction of ID1 expression." (PMID 33990575, 2021). "Sh-Nur77 tumors showed higher ID1 expression, which may be responsible for hepatic metastasis of colon cancer cells." (PMID 33990575, 2021). "We hypothesized that these putative enhancers regulate ID1 expression in colon cancer." (PMID 37373188, 2023). "However, we did not observe a correlation between TGFβ signal activity and ID1 expression in Smad4-deficient clinical colon cancer samples." (PMID 33990575, 2021). "Both ID1 and ID3 regulate self-renewal of colon cancer stem cells and play a role in resistance to the chemotherapy drug oxaliplatin." (PMID 38195969, 2024). "TGFβ substantially induced ID1 messenger RNA (mRNA) and protein expression in LS174T colon cancer cells." (PMID 33990575, 2021). "To exclude Smad3/Smad4-mediated transcriptional induction of ID1, we used Smad4-null SW620 and HT29 colon cancer cells." (PMID 33990575, 2021). "Colon cancer stem cells exhibited high ID1/ID3 expression and p21 expression; the knockdown of ID1/ID3 decreased p21 expression and decreased the tumorigenic potential of colon cancer stem cells." (PMID 29652830, 2018). "The results of these experiments provided evidence that ID1 and ID3 function together to control the self-renewal of colon cancer stem cells through cell-cycle restriction driven by the cell-cycle inhibitor p21." (PMID 29652830, 2018).
colon cancer (continued). "It has been reported that ID1 and ID3 govern self-renewal and cell cycle restriction on cancer stem cell (CSC) populations of colon cancer through regulation of p21." (PMID 27650540, 2016). "Notably, previous studies have shown that ID1, ID3, and c-MYC help maintain the self-renewal capacity of colon cancer stem cells." (PMID 40399276, 2025). "ID1 and ID3 regulate the self-renewal of colon cancer stem cells through p21." (PMID 38195969, 2024). "In human colon cancer cells, ectopic STAT3 expression increased ID1 mRNA and protein expression." (PMID 38183094, 2024). "Furthermore, colon cancer cells, namely, HT29, SW620, and SW837 when treated with dinaciclib showed decreased the expression levels for LGR5, ID1, and CD44v9." (PMID 38182897, 2024). "Moreover, PAF1 knockdown decreased the expression levels of the genes such as LGR5, ID1, ID3, CD44v9, CD133, BMI1, RNF43, EPHB2, SOX9, and ASCL2, which are critical for inducing colon cancer stemness and its markers." (PMID 38182897, 2024). "c-Myc, Snai1, and Id1, but not Tcf4 and Id2, were found to be highly expressed in the colon cancer cell-derived CM-treated group compared to the control (Ctrl) group." (PMID 37996458, 2023). "Importantly, the silencing of ID1 and ID3 increases the sensitivity of colon cancer stem cells to chemotherapeutic agents such as oxaliplatin." (PMID 29652830, 2018). "Recently, Id1 and Id3 co-expression (but not its individual expression) has been proposed as a novel mechanism of regulation of the self-renewal capacity of human colon cancer-initiating cells (CC-ICs)." (PMID 23311395, 2013). "Moreover, Nur77 was inversely correlated with ID1 expression in HCT116 and RKO colon cancer cells." (PMID 33990575, 2021).
lung adenocarcinoma (16 papers, 2010 to 2025). A carcinoma that arises from the lung and is characterized by the presence of malignant glandular epithelial cells. "MiR-381 is decreased in lung adenocarcinoma tissues, and miR-381 binds to ID1 and inhibits its expression." (PMID 33324542, 2020). "A previous study reported that ID1 is overexpressed in lung adenocarcinoma and that ID1 expression correlates with that of Src and MMP9, which are associated with EMT." (PMID 33324542, 2020). "To assess how baicalein inhibits the expression of Id1 protein, we analyzed the effect of baicalein to Src and its phosphorylation as studies show that Src regulates the expression of Id1 in human lung adenocarcinoma and pancreatic adenocarcinoma." (PMID 30949224, 2019). "In a previous study, we showed that a high Id1 protein expression is an independent prognostic biomarker in patients with adenocarcinoma of the lung, regardless the stage." (PMID 23311395, 2013). "Studies of Id1 expression in primary human NSCLCs demonstrated lower Id1 expression in adenocarcinomas of the lung when compared to squamous cell carcinomas with variable expression compared to matched normal lung tissues." (PMID 20414347, 2010). "Among the 14 lung adenocarcinomas, we observed elevated Id1 expression in tumor specimens versus normal lung in 5 cases with no notable association with tumor stage at the time of diagnosis." (PMID 20414347, 2010). "We find Id1 expression is upregulated in squamous cell carcinoma when compared to adenocarcinoma of the lung and that expression of Id1 versus the normal control is variable in NSCLCs." (PMID 20414347, 2010). "In vivo experiments in KRAS-mutant syngeneic and metastatic murine lung adenocarcinoma models showed that the combined blockade targeting Id1 and PD-1 was more effective than each treatment alone in terms of tumor growth impairment and overall survival improvement." (PMID 33126649, 2020). "Another study showed that ID1 expression could be an independent prognostic factor in lung adenocarcinoma patients." (PMID 33324542, 2020). "In lung adenocarcinoma, miR-381 inhibits ID1 and suppresses EMT." (PMID 33324542, 2020). "We described that Id1 expression was a poor prognostic marker for lung adenocarcinoma." (PMID 23311395, 2013). "Interestingly, our study indicates that patients with lung adenocarcinomas express lower levels of Id1 when compared to patients with squamous cell carcinomas although neither level is consistently above that expressed in surrounding normal tissues." (PMID 20414347, 2010). "Notably, ID1 expression is lost in most of metastatic human lung adenocarcinoma specimens." (PMID 33917757, 2021). "Furthermore, in lung adenocarcinomas, it was found that the decreased level of miR-381 may contribute to metastatic potential by targeting ID1." (PMID 26688820, 2015). "In addition, miR-381 was reported to suppress the expression of ID1 in lung adenocarcinoma." (PMID 26688820, 2015). "In this study, we explored the potential synergistic effect of the combination of Id1 inhibition and pharmacological PD-L1 blockade in three different syngeneic murine KRAS-mutant lung adenocarcinoma models." (PMID 33126649, 2020). "Since the vast majority of specimens were lung adenocarcinomas (AD) or squamous cell carcinomas (SCC), tumors were sorted based on this distinction to further evaluate Id1 expression trends." (PMID 20414347, 2010). "Here we aimed to test whether a combined blockade of Id1 and PD-1 is able to improve outcomes of mice models with KRAS-driven lung adenocarcinoma." (PMID 33126649, 2020). "Recently, Id1 has been identified as an independent prognostic factor in patients with lung adenocarcinoma, regardless of the stage." (PMID 23311395, 2013).
lung adenocarcinoma (continued). "Boxplot analyses for all specimens did not demonstrate significant differences between either lung adenocarcinomas or squamous cell carcinomas and normal tissues; however, statistically increased Id1 expression was nearly achieved for squamous cell carcinomas versus adenocarcinomas (P = .0579)." (PMID 20414347, 2010).
gastric cancer (15 papers, 2007 to 2025). A primary or metastatic malignant neoplasm involving the stomach. "In addition, there were significant association between ID1 expression in peripheral blood and those in bone marrow from gastric cancer cases." (PMID 19491902, 2009). "Thus, the loss of feedback regulation among PTBP3, Id1, and Hes1 in gastric cancer cells may be one of the causes of inhibited differentiation and malignant proliferation of these cells." (PMID 32974175, 2020). "The expression level of ID1 protein in gastric cancer tissues was significantly higher than that in surrounding tissues." (PMID 39619441, 2024). "ID1 expression positively correlated with the degree of differentiation, invasion, and metastasis of gastric cancer." (PMID 39619441, 2024). "High expression of Id1 has been confirmed in gastric cancer tissues and cell lines, suggesting that it plays a critical role in the occurrence of gastric cancer." (PMID 32974175, 2020). "For example, Id-1 silencing significantly suppressed the gastric cancer cell migration and invasion in vitro." (PMID 29233161, 2017). "In the study, collagen hydrogel was used as carriers to test the feasibility of localized and sustained delivery of Id1-targeted siRNA for in vivo gastric cancer inhibition." (PMID 27029190, 2016). "Previous studies showed that Id1 is a prognostic marker in patients with gastric cancer which is involved in the growth and migration of gastric cancer cells." (PMID 27029190, 2016). "In the study, we chose Id1 as target gene aiming to investigate the inhibitory efficacy of collagen-based in vivo siRNA delivery on gastric cancer." (PMID 27029190, 2016). "In gastric cancer, several genes have been proved to be closed related to proliferation and migration of gastric cancer cells, such as Stathmin1, Id1, PLCE1." (PMID 27029190, 2016). "In this study, we mainly investigated the feasibility of localized and sustained delivery of Id1-targeted siRNA which has been incorporated into collagen and its effect on the growth and migration ability of gastric cancer cells both in vitro." (PMID 27029190, 2016). "Further research have showed that down-regulation of Id1 by small interfering RNA in gastric cancer inhibits cell growth via the Akt pathway." (PMID 27029190, 2016). "Inhibitor of DNA binding 1 (Id1) is a member of the helix-loop-helix transcription factor family that is overexpressed in various types of cancer, including gastric carcinoma." (PMID 27029190, 2016). "After poorly differentiated AGS gastric cancer cells were treated with siRNA-Id1, proliferation slowed significantly, thus inhibiting Id1 mRNA and protein expression." (PMID 23900621, 2013). "The number of peritoneal metastases is significantly reduced, and the size of single metastases is also decreased, which proves that Id1 and Id3 knockout can significantly inhibit peritoneal metastasis of gastric cancer cells." (PMID 23900621, 2013). "In gastric cancer, Id1 was nuclear in well-differentiated carcinoma, but was cytoplasmic in moderately to poorly differentiated carcinoma." (PMID 23342268, 2012). "The ID1 protein expression in bone marrow was evaluated immunohistochemically in studies of metastatic gastric cancer patients and healthy volunteers." (PMID 19491902, 2009). "In the peripheral blood samples, there was a significant relationship between the expression level of ID1 mRNA and the progression of gastric cancer cases." (PMID 19491902, 2009). "In this study, we investigated the clinical significance of the ID1 mRNA expression in bone marrow and peripheral blood samples obtained from gastric cancer patients." (PMID 19491902, 2009). "We examined the ID1 protein expression immunohistochemically in 30 primary lesions, 3 metastatic lymph nodes and 3 peritoneal disseminated lesions of gastric cancer cases." (PMID 19491902, 2009). "In gastric cancer cells, Id1 could be dose-dependently decreased by sulindac sulfide, a non-steroidal anti-inflammatory drug." (PMID 28122577, 2017).